CCL5 (C-C motif chemokine ligand 5)
Diseases named in the same sentence as CCL5 in open-access papers (continued):
Sharing a sentence is not in itself a finding about the gene and the disease.
tumor (continued). "In particular, we discovered that E. coli MG1655 reprogrammed tumor-associated macrophages into the M1 phenotype, which secreted CCL5 to recruit the adoptively transferred T cells." (PMID 39572541, 2024). "Overall, these data suggest that increased expression of CSF-1 in EBV-associated tumour cell CM can upregulate CCR5 receptor expression on monocytes and migration towards increased CCL5 in EBV-associated tumour cell CM." (PMID 39267775, 2024). "This modification promotes the CyPA‐CD147 interaction and in turn increases NSCLC cell‐derived CCL5 secretion by activating p38‐ZBTB32 signaling, which facilitates M2‐tumor‐associated macrophage infiltration in NSCLC tissues via the CCL5/CCR5 axis." (PMID 38873823, 2024). "Analysis of NK cells at 24 h post-photoconversion revealed that production of CCL5 was restricted to KG+ CD11b+ CD49a- NK cells, confirming the rapid loss of CCL5 expression after tumor entry." (PMID 38267402, 2024). "An oHSV engineered to express EGFR antibody cetuximab linked to the chemotactic chemokine CCL5 enhanced chemotactic and activation immune cells, inhibited tumor EGFR signaling, reduced tumor size and prolonged survival in glioblastoma-bearing mouse models." (PMID 39518074, 2024). "Targeting Beclin-1, an autophagy-related gene, causes functional NK cell infiltration into the tumor microenvironment (TME) by releasing C-C motif chemokine ligand 5 (CCL5)/RANTES from tumor cells." (PMID 38627815, 2024). "Due to its ability to bind multiple receptors, CCL5 has been linked to multiple pathways that mediate tumor progression, including the JAK2/STAT3, NF-κB, TGFβ, PI3K/Akt, HIF-α, and Ras-ERK-MEK pathways." (PMID 39409924, 2024). "It was evident that IRF‐score is strongly associated with multiple chemokines and receptors in 12 tumours, in particular CCL5, CCR2/4/5, CXCL9/10/11 and CXCR3 (p < 0.05)." (PMID 38130025, 2024). "The depletion of tumor-associated macrophages or CCL5 neutralization in vivo leads to the significantly decreased solid tumor infiltration of adoptive T cells in the presence of bacteriotherapy." (PMID 39572541, 2024). "The increased level of LPE in the Arf1-deficient tumor cells sequestrated PPARγ from the PPARγ-NF-κB complex, which freed NF-κB for regulating CCL5 and T-cell tumor infiltration." (PMID 39872623, 2023). "As seen in PCa, primary breast cancer tumors recruit CXCR6 expressing MSCs via CXCL16, and the tumor-associated MSCs then secrete other chemokines, such as CCL5 and CXCL10, that promote invasion and metastasis." (PMID 37025604, 2023). "Bartlett’s group demonstrated that oncolytic VACVs encoding CCL5 or CXCL11 elicited potent anti-tumor immunity and enhanced therapeutic efficacy by attracting activated immune cells such as T (Th1) and NK cells." (PMID 38283361, 2023). "Tumor-associated MSCs in the bone microenvironment activate the inflammatory NF-kB signaling cascade and induce the secretion of the cytokine CCL5, which contributes to OS migration and metastasis." (PMID 37206921, 2023). "CCL2, ARG1, ARG2, NOS2, and CCL5 are well-known N2-associated cytokines that promote tumor growth, invasion, and immune suppression." (PMID 37174093, 2023). "Surgery has also been found to affect the number of TAMs, the level of IL-6, and the level of chemokine (C-C motif) ligand 5 (CCL5), all of which are associated with angiogenesis, cell migration, and tumor cell invasion in TNBC." (PMID 37512096, 2023). "Conversely, CCL5 is also associated with cancer progression and metastasis by promoting the survival, proliferation, and infiltration of tumor cells." (PMID 38092882, 2023). "For CCL5-deficiency MDSC-DCs, we constructed tumor models developed in CCL5-knockout mice and induced MDSCs via GM-CSF and IL-4 into CCL5−/−MDSC-DCs." (PMID 35707772, 2022).
tumor (continued). "Various secreted factors associated with TAMs are also potential biomarkers, such as Tim-3 which correlates with increased tumour invasion and lymph node metastasis and CCL5/RANTES and NFKB1 where SNPs are associated with altered clinical outcome." (PMID 36139540, 2022). "CCL5 commonly expresses in inflammatory environment and plays a part in tumor-associated immunoregulation." (PMID 36031660, 2022). "CCL5 levels ≤ the criterion at baseline (59959 pg/ml) were associated with relative tumor shrinkage (P = 0.021), better progression-free survival (PFS) (P = 0.036), and overall survival." (PMID 36387070, 2022). "It was reported that, in tumor-associated fibroblasts (CAFs), HIF-1α activates the NF-κB signaling pathway causing an increase in the expression level of CCL5, which promotes tumor growth." (PMID 35682354, 2022). "Some studies accounted CCL5 for the promotion of tumor development by suppressing the immune response, whereas some studies regarded CCL5 as a tumor protective factor associated with high CD8+ T cell infiltration." (PMID 35252266, 2022). "Several studies have found that CCL5 as the chemostatic factors of tumor cells is closely associated with the proliferation, invasion and metastasis." (PMID 36514094, 2022). "High CCL2 and CCL5 expression was associated with tumor metastasis and poor prognosis in BC patients." (PMID 36438499, 2022). "Previous reports showed that CLIC4-deficient mice had lower circulating levels of CCL5 than controls after LPS treatment, a finding we now extend to plasma of tumor-bearing mice." (PMID 35727842, 2022). "Although elevated levels of C-C chemokine ligand 5(CCL5) were detected in a variety of tumours and were associated with tumour progression, CCL5 also exhibited antitumour abilities by recruiting T cells and dendritic cells to the TME." (PMID 34776511, 2021). "Given that MEKK1-deficient fibroblasts showed both reduced CCL5 expression and diminished ability to induce tumor cell invasion, we decided to examine the importance of breast stroma-derived CCL5 in MDA-MB 231 tumor cell migration." (PMID 33868996, 2021). "CCL5, also known as RANTES, is a chemokine associated with tumor-infiltrating lymphocytes and is secreted by T lymphocytes, macrophages, and certain tumor cells." (PMID 34716323, 2021). "CCL5 from tumor cells or tumor-associated myeloid cells appears to license CXCL9 production almost exclusively from inflammatory CD68+ macrophages and CD11c+ DCs within the TME." (PMID 34354714, 2021). "CCL5 chemokine as well as its receptor CCR5 have been linked to the promotion of the angiogenesis during tumor cells evasion through the recruitment of inflammatory cells." (PMID 34976001, 2021). "Analysis of publicly available tumor transcriptome profiles showed that the chemokine CCL5 was strongly associated with immune cell infiltration in various human cancers." (PMID 34030676, 2021). "Secretion of CCL5 by fibroblasts in the tumor tissue is associated with changes of tumor cell behavior to more aggressive, the recruitment of immunosuppressive cells, and the activation of angiogenesis." (PMID 34101732, 2021). "We generated TEMs in vitro using EVs from sgCCL5 or control TNBC cells, and identified TEM cytokines whose expression was decreased upon loss of tumor cell CCL5 expression." (PMID 34298673, 2021). "Such infiltration was associated with the release of CCL2 and CCL5 chemokines in the tumor microenvironment." (PMID 34155342, 2021). "Immunosuppressive M2-tumour-associated macrophages (TAMs) can be reprogrammed to an anti-tumoural M1-TAM subtype by targeting the CCR5/CCL5 axis." (PMID 34638423, 2021). "CXCL9 and CXCL10 had functions in the tumor microenvironment, such as regulating T cell differentiation and directing the migration of immune cells to tumor tissues, while CCL5 was thought to be associated with graft-versus-host disease." (PMID 34727927, 2021).
tumor (continued). "The particular case of CCL5 highlights the challenges of understanding and modulating the complex pathways underlying the tumor microenvironment." (PMID 34030676, 2021). "Previous studies have shown that CCL5 secreted from tumor-associated macrophages (TAMs) promoted progression in prostate, gastric and colorectal cancers." (PMID 33671956, 2021). "More specifically, the activation of NF-kB in tumor cells enhances the expression of several genes (including Ccl7, Cxcl1, Ccl5, Slc39a10, Lcn2, Zc3h12a, and Enpp2) that are implicated in tumor migration, angiogenesis, and formation of pre-metastatic niches." (PMID 33567747, 2021). "In our study, we have found CCL5 is mainly expressed in cancer cells and tumor-associated lymphocytes." (PMID 34771505, 2021). "Cytokines, such as CCL5 and IL-8 can be secreted by macrophages and tumor-associated DCs, which interact with the receptors expressed in the tumor cells." (PMID 32083005, 2020). "Overexpression of CCL5 was correlated with ERK phosphorylation in tumor cells, and was statistically associated with poor disease-free survival and overall cancer survival in patients with early HER2-positive BC." (PMID 32787888, 2020). "Chemokines including CCL2 and CCL5 are described to attract tumor-associated macrophages and monocytes during this infiltration process." (PMID 33207809, 2020). "CD4+ tumor-associated lymphocytes express CCL5, and coculture with GC cells further increases CCL5 secretion by CD4+ T cells." (PMID 32630699, 2020). "Phyllodes tumors of the breast promote malignant progression by secreting CCL5 to recruit macrophages associated with repolarized tumors." (PMID 33224886, 2020). "The roles of CCL5 in cancer biology are versatile as this ligand not only triggers antitumor immune responses but also is implicated in tumor progression and metastasis formation." (PMID 32425930, 2020). "By contrast, increased CCL5 expression resulting from RUNX3 mutation is associated with more tumor metastasis in the lung." (PMID 32218434, 2020). "•Metastatic CSMD3 mutated HGSOC showed objective and sustained response to pembrolizumab.•The tumor was massively infiltrated by CD8+ T cells while PD-L1 TPS was at 10%.•CSMD3 mutated HGSOC showed up-regulation of CCL5 and CXCL9." (PMID 32613071, 2020). "Although CCL5 is implicated in tumour progression and its elevated levels are detected in several cancers, it also promotes anti-tumour immunity via the recruitment of T cells and dendritic cells to the TME40." (PMID 33116132, 2020). "MDSCs can induce the chemokines CCL4 and CCL5 to recruit Treg to the tumor sites and cause immunosuppression." (PMID 32823603, 2020). "Higher levels of CCL5 were also detected in the tumor supernatant of Caspase-1-deficient tumors consistent with an increase in NK cells recruitment and activation." (PMID 33042810, 2020). "Among them, the nerve growth factor (NGF) and the brain-derived neurotrophic factor (BDNF) cause axonal chemoattraction, and IL-6, IL-8, IL1b, and CCL5 foster tumor-associated hyperalgesia." (PMID 30825056, 2019). "In wild type and S100A4-deficient mouse models, tumor cell-derived CCL5 on S100A4 release into blood circulation ultimately increases the metastatic burden in mice." (PMID 30925930, 2019). "Here, important chemoattractants such as Ccl20 and Ccl5 were downregulated in the microarray of IL-6Rα-deficient tumours." (PMID 29695802, 2018). "Higher CCL5 levels were associated with lower histological differentiation, higher depth of tumor invasion, more frequent lymph nodes involvement, and advanced tumor stage." (PMID 29772686, 2018). "Here, we demonstrated that CCL5-deficiency delayed tumor growth and metastasis via facilitating CD8+ T cells to accumulate into tumor site in CRC mouse models." (PMID 29991744, 2018).
tumor (continued). "Collectively, these results demonstrated that CCL5-deficienty promotes the migration of CD8+ T cells into tumor and increases the antitumor immune response of CD8+ T cells to inhibit tumor growth and metastasis." (PMID 29991744, 2018). "Previous studies have shown that the expression level of CCL5 is associated with tumor growth and metastasis formation in several types of cancers." (PMID 29991744, 2018). "IL-1ra, IL-12, IL-17, FGFb, Mip-1α and Rantes (CCL5) serum levels were associated with the tumor type (p = 0.027, p = 0.008, p = 0.002, p = 0.040, p = 0.011, p = 0.011)." (PMID 28537901, 2017). "In tumor lesions, the local expression of CCL5 was negatively associated with the expression of IGF1R." (PMID 29156819, 2017). "In tumor lesions, the local expression of CCL5 was positively associated with the expression of the CD8+ T lymphocyte marker CD8 (r=0.4203, p=0.0007)." (PMID 29156819, 2017). "In tumor lesions, the local expression of CCL5 was negatively associated with the expression of the IGF1R (r =-0.6614, p< 0.0001)." (PMID 29156819, 2017). "In this work, we demonstrate that distinct tumor angiogenesis defects associated with suppression of cancer cell CCL5 are associated with a reduced number of tumor EPCs, and a reduction in the number of CEPs." (PMID 27863423, 2016). "By contrast, local ionizing radiation coupled with vaccination increased CD8+ T cell infiltration that was associated with upregulation of CXCL10 and CCL5 chemokines in the tumor, but demonstrated modest inhibition of tumor growth." (PMID 27343548, 2016). "A literature examination of the missing cytokines (IL6, IL8, LCN2, MCP1, and CCL5) indicated that most of them have indeed been implicated in tumor growth, tumor angiogenesis, or tumor invasion." (PMID 26959742, 2016). "A variety of chemokines, like CCL2 and CCL5, have been detected in neoplastic tissues and associated with tumor associated immune cells formation and recruitment." (PMID 26790618, 2016). "The chemokine ligand 5 (CCL5) levels ≤ cut-off value (59959 pg/ml) at baseline was associated with relative tumor shrinkage (P = 0.021), better progression-free survival (PFS) (P = 0.036) and overall survival (OS) (P = 0.019)." (PMID 27166185, 2016). "OPN potentiated tumor growth via interaction with mesenchymal stromal cell to upregulate expression of CCL5 and cancer-associated fibroblast markers including SDF-1." (PMID 26106421, 2015). "Bone-marrow-derived mesenchymal stem cells have been found to integrate into the tumor-associated stromal and secrete CCL5 which then acts in a paracrine way on the cancer cells to enhance their invasion." (PMID 24591756, 2014). "Intratumoral injection of CCL4 or CCL5 increased tumor-infiltrating Tregs, and deficiency of CCR5 led to their profound decrease, emphasizing the importance of CCR5 in the control of antitumor immune responses." (PMID 24591756, 2014). "Mast cell activation by complement C5a will cause CCL2 and CCL5 upregulation, which has been to shown to induce Tumor Associated Macrophages (TAMs) to release IL-10, promote angiogenesis, and stimulate tumor metastasis." (PMID 24949488, 2014). "The interleukin-6 (IL-6) and the chemokine CCL5 are implicated in the development and progression of several forms of tumours including that of the prostate." (PMID 19242540, 2009). "In summary, signaling and functional assays in CRC cell lines showed that PDGF-BB–mediated PDGFRβ activation remodels the secretome of tumor-associated fibroblasts—especially by increasing the release of CCL5 and CXCL12—thereby promoting CRC cell proliferation and migration." (PMID 41601676, 2026). "Specifically, tumor cells induced secretion of CCL2 (C-C motif chemokine ligand 2), leading to macrophage activation and subsequent TWEAK secretion by tumor cells via the CCL5/TRAF6 (TNF receptor-associated factor 6)/NF-κB signaling axis, which stimulated muscular atrophy." (PMID 40427186, 2025).
tumor (continued). "In CCL5-deficient mice, both primary tumor burden and pulmonary metastases are markedly reduced." (PMID 40909271, 2025). "Furthermore, elevated expression of CCL5 is associated with poor prognosis in BC, particularly in its role in promoting tumor invasiveness and metastasis." (PMID 40496857, 2025). "Consequently, this up‐regulation of CCL5 drives the infiltration of tumor‐associated macrophages (TAMs) and their polarization toward the M2 phenotype, ultimately facilitating tumor angiogenesis and growth." (PMID 40536254, 2025). "This CCL5 upregulation facilitated immunosuppressive M2-like tumor-associated macrophage (TAM) infiltration in NSCLC via the CCL5/CCR5 axis in intercellular crosstalk between tumor cells and macrophages, a process reversed by blocking CD147-K148me2 with the targeted antibody 12C8." (PMID 40586874, 2025). "Additionally, CCL5+ tumor-associated macrophages infiltration correlates with poor prognosis, highlighting its clinical significance." (PMID 40396123, 2025). "For instance, CCR5 ligands (CCL3, CCL4, CCL5) have been shown to induce the proliferation of CCR5-expressing MDSCs in the bone marrow, while CCL5 deficiency adversely modulated the morphology, differentiation, and immunosuppressive activity of MDSCs, ultimately inhibiting tumor growth." (PMID 39990210, 2025). "In addition, according to the K–M analysis, positive CCL5 expression in the IC was associated with shorter RFS in the following subgroups: tumor stage 3 + 4 (p < 0.001), N0 (p = 0.030), N1/N2 (p = 0.039) and no chemotherapy (p < 0.001)." (PMID 38928033, 2024). "In addition to CCL5/IFNG expression in the diagnostic tumor biopsy our study also discloses the potential role of serum CCL5 and CXCL9 as early biomarkers of response to neoadjuvant treatment with anti-HER2 antibodies." (PMID 38167224, 2024). "CCL5 is often seen as a “double-edge sword” in cancer, since it has been associated both with promoting antitumor immunity, as well as being implicated in tumor growth and migration." (PMID 38172127, 2024). "Furthermore, positive CCL5 expression in the IC was associated with shorter DSS in the following subgroups: tumor stage pT3 + 4 (p = 0.003), N0 (p = 0.037), NX (p = 0.035), and no chemotherapy (p < 0.001)." (PMID 38928033, 2024). "Notably, CCL5 (chemokine ligand 5), whose expression is associated with recruitment of NK cells and dendritic cells in the tumor microenvironment, was robustly up-regulated upon treatment with UMCD6 (**p < 0.01)." (PMID 38280067, 2024). "Additionally, CCL5 expression in these tumor cells was linked to an increased risk of both overall and disease-specific death." (PMID 39409924, 2024). "Additionally, cytokine granulocyte-macrophage colony stimulating factor (GM-SCF) encoding gene CSF2 and chemokine CCL5 encoding gene CCL5 were specifically expressed in TEx cells, which recruted Treg cells into tumor microenvironment and promoted tumor growth." (PMID 37550396, 2023). "In addition, a CCL5 chemokine derived from tumor associated macrophages such as CCL5, not only support the rejuvenation and tumorigenicity of PCSCs, but also promote PCSC metastasis via activating the β-catenin/STAT3 signaling pathways." (PMID 36969009, 2023). "The pro-inflammatory factors CCL-2 and CCL-5 were reportedly associated with tumor growth, angiogenesis, and invasion of breast cancer, while CCL-2 could indirectly stimulate tumorigenic activity of normal breast cells." (PMID 35663394, 2022). "Ginseng-derived nanoparticles can reprogram tumor-associated macrophages in colon cancer to increase CCL5 and CXCL9 secretion and recruitment of CD8+ T cells into the tumor bed; these nanoparticles synergized with PD-1 mAb therapy with no detected systemic toxicity." (PMID 36386161, 2022). "CCL-5 secreted by tumor-associated macrophages (TAMs) might promote the progression of prostate, gastric and colorectal cancers." (PMID 35663394, 2022).